MYOC (myocilin)
Diseases named in the same sentence as MYOC in open-access papers (continued):
Sharing a sentence is not in itself a finding about the gene and the disease.
glaucoma (continued). "In the current study, we performed MYOC mutation screening in a large glaucoma family affected with POAG, and our results suggest that novel mutations of MYOC, Pro13Leu and Gln337Stop, may be associated with POAG." (PMID 18776955, 2008). "Increased extracellular levels of mutant myocilin expressed in heterozygosis may play a relevant role in glaucoma pathogenesis." (PMID 19023451, 2008). "Nonreducing SDS-PAGE indicated that extracellular myocilin resulting from 24 h co-expression of wild-type myocilin and each of the 4 missense mutants forms hetero-oligomers and that glaucoma mutations do not increase the size of myocilin aggregates." (PMID 19023451, 2008). "Some hypotheses have been proposed over recent years in an attempt to explain myocilin glaucoma pathogenesis." (PMID 19023451, 2008). "We speculate that the extracellular presence of mutant myocilin could be a key element in the molecular mechanisms that lead to glaucoma." (PMID 19023451, 2008). "At present, screening tests in whole populations for MYOC defects are not feasible due to the low prevalence of MYOC-associated glaucoma." (PMID 18776955, 2008). "Pre-symptomatic screening for glaucoma is an attractive prospect and although it may be currently uneconomical to introduce MYOC gene screening in a population-wide approach, targeted screening is warranted in selected populations." (PMID 17417609, 2007). "In any event, it is unlikely that changes in the gene expression may contribute to myocilin glaucoma since development of the disease appears to be related with structural alterations of the protein." (PMID 17615537, 2007). "Also, haploinsufficiency of MYOC in patients due to either homozygous R46X truncation or hemizygous interstitial deletion on 1q24-q26 does not cause glaucoma." (PMID 40385286, 2025). "Multiple studies on myocilin variants have supported the conclusion that deleterious mutations in the OLF domain result in the aggregation of insoluble and soluble misfolded proteins within the trabecular meshwork, leading to POAG in millions of hereditary glaucoma cases." (PMID 40458333, 2025). "Thus, strategies to ameliorate the underlying pathogenesis of myocilin-associated glaucoma with antibodies poses challenges not present in better studied misfolding systems." (PMID 39726989, 2025). "Mutation in MYOC and OPTN, the high penetrance glaucoma genes, is responsible for about 4% of POAG conditions globally whereas the remaining is likely attributed to a combination of both environmental and genetic factors contributing to the complex inheritance of glaucoma." (PMID 37962455, 2024). "Despite its widespread expression, MYOC does not appear essential for ocular health, as evidenced by both KO animal models and individuals with homozygous, likely null mutations who do not exhibit glaucoma phenotypes." (PMID 38671671, 2024). "Unlike glaucoma associated with MYOC mutations, i.e., juvenile primary open-angle glaucoma, which has a normal outflow route at birth, the FOXC1 gene mutations identified in this study caused severe angle abnormalities, resulting in perinatal onset of glaucoma." (PMID 39158757, 2024). "However, not all mutations in MYOC cause glaucoma, and common variants are expected to be neutral polymorphisms." (PMID 36579626, 2023). "In addition, there is an age at diagnosis for variants now considered benign because individuals harboring myocilin polymorphisms can still develop glaucoma even if the relationship is not causal." (PMID 36579626, 2023). "However it is unclear how N450Y mutant myocilin (MYOC)-induced ER stress impairs TM cells and whether N450Y mutant MYOC proteins are associated with the development of glaucoma in vivo." (PMID 35615698, 2022).
glaucoma (continued). "In addition, we identified several transcriptional targets of GLIS1 in TM cells that previously have been implicated in TM-related functions, IOP homeostasis, and ocular hypertension/glaucoma, including MYOC, ADAMTS10, LTBP2, LOXL1, TGFBR3, CYP1B1, and EFEMP15,28,43,44." (PMID 34385434, 2021). "In addition, such myocilin inclusion bodies are found in about 70–80% of all glaucoma cases." (PMID 33925820, 2021). "Therefore, it has been suggested that MYOC mutations and the aggregation of mutant myocilin in the ER of TM may cause cell stress, resulting in reduced cell function, decreased outflow of aqueous humor, and increased IOP, a glaucoma risk factor." (PMID 34828408, 2021). "Therefore, enhanced autophagy, which degraded the misfolded myocilin and other increased extracellular matrix, might restore TM function and reduce pathological changes in glaucoma." (PMID 32714192, 2020). "Similarly, in a population from Quebec, mutations in MYOC have been associated with glaucoma, but these reports have not been consistent when applied to other populations." (PMID 33396423, 2020). "Also, retinol-binding protein 3, retinal dehydrogenase 2 and retinoic acid receptor responder protein 2 could be identified, which is interesting since TM expression of glaucoma-related myocilin was demonstrated to be regulated by retinoic acid." (PMID 31121981, 2019). "Although these hypotheses await to be confirmed, identifying bicarbonate as a factor that regulates recombinant myocilin secretion and proteolytic cleavage, might open up new avenues to understand the biological function of this protein in the eye and in glaucoma pathogenesis." (PMID 23342144, 2013). "Screening for MYOC mutations was performed in 207 index patients: 96 with adult-onset primary open-angle glaucoma (POAG), 21 with primary congenital glaucoma (PCG), 18 with juvenile-onset open-angle glaucoma (JOAG), five with Axenfeld-Rieger syndrome (ARS), and 67 with other types of glaucoma." (PMID 23922489, 2013). "Thus, it is important to screen other glaucoma-associated loci and genes for involvement in congenital glaucoma in cases that are either negative or heterozygous for MYOC, CYP1B1, and FOXC1 mutations to have better insight into the disease pathogenesis." (PMID 23378721, 2013). "As a glaucoma protein, myocilin is not alone in its association with the endocytic pathway." (PMID 24367514, 2013). "Hence any mutation in CYP1B1 that reduces its 17β estradiol metabolizing activity might lead to MYOC upregulation, which in turn might play a role in glaucoma pathogenesis." (PMID 23028769, 2012). "Increasing evidence showed that the modulation of the wild-type (wt) myocilin protein expression is not causative of glaucoma while some misfolded and self-assembly aggregates of mutated myocilin may be associated with POAG in related or unrelated populations." (PMID 21709622, 2011). "Both thermodynamics and kinetics may be important in chaperone therapy for myocilin glaucoma." (PMID 21283635, 2011). "Its function is unknown and the mechanisms by which mutations in MYOC cause glaucoma are not understood." (PMID 19148291, 2009). "It is interesting to note that secretion and processing of myocilin mutations associated with Mendelian cases of glaucoma did not differed significantly from those found in non-Mendelian glaucoma, indicating that other factors should determine the type of inheritance." (PMID 19023451, 2008). "Our hypothesis does not exclude other proposed mechanisms of myocilin associated glaucoma, instead it complement the current view of glaucoma pathogenesis." (PMID 19023451, 2008). "Most of these hypotheses do not consider that MYOC mutations involved in glaucoma are usually present in heterozygosis." (PMID 19023451, 2008). "However, both the actual molecular mechanism by which reduction of the processed myocilin may lead to glaucoma and the physiologic signal(s) that trigger myocilin processing remain to be elucidated." (PMID 19023451, 2008).
glaucoma (continued). "Therefore, we analyzed by nonreducing SDS-PAGE and western blot whether heterozygous expression of myocilin glaucoma mutants affected myocilin self-aggregation." (PMID 19023451, 2008). "The integrated system significantly reversed glaucoma-induced changes in TNF-α, IL-8, MYOC, NRF2, TIMP1, and IL-1β levels, resembling those of the healthy group." (PMID 40643885, 2026). "In a Cre-inducible Tg.CreMYOCY437H glaucoma mouse model, LNP-Cre mRNA selectively induced mutant MYOC expression in the TM, faithfully recapitulating key disease features." (PMID 41657308, 2026). "Previously, we have shown that helper adenovirus (HAd) 5-Cre induces mutant MYOC in the TM, elevating IOP and leading to glaucoma in Tg-CreMYOCY437H mice." (PMID 41210166, 2025). "Through this brief study, we aim to uncover the pathogenicity of the E414K substitution and promote continued research into other myocilin VUS, in the hope of advancing genetic research into POAG and the definitive treatment of glaucoma." (PMID 40458333, 2025). "Because MYOC variants have an autosomal dominant inheritance and CYP1B1 variants have an autosomal recessive inheritance, a multi‐generation family history of glaucoma could support the presence of MYOC variants, whilst an absence of family history could suggest CYP1B1 variants." (PMID 39929609, 2025). "Lipoplex carrying Cre mRNA produced mutant MYOC in the TM, elevating IOP and leading to the development of glaucoma in Tg.CreMYOCY437H mice." (PMID 41210166, 2025). "Myocilin (MYOC) was identified by Stone and colleagues in the GLC1A locus, which was the first reported locus for primary open-angle glaucoma (POAG) located on chromosome 1." (PMID 39456800, 2024). "In conclusion, our studies show that LVs are highly efficient in delivering Cas9 to TM without any ocular toxicity and LV-mediated gene editing is highly efficient in reducing mutant myocilin and lowering elevated IOP in mouse model of glaucoma." (PMID 38521856, 2024). "However, the pathogenesis of glaucoma induced by MYOC mutations has not been fully clarified." (PMID 36267417, 2022). "Interestingly, mutated MYOC induces the overexpression of GRP78 chaperones as well as the protein disulfide isomerase, which triggers perturbations in TM cellular morphology and normal cell proliferation, that may play a pivotal role in glaucoma pathogenesis." (PMID 33925820, 2021). "Reduction of CHOP or treatment with autophagy inducers corrected impaired autophagy flux, which resulted in better cargo recognition, promoting efficient autophagic degradation of mutant myocilin and reducing elevated IOP in the mouse model of glaucoma." (PMID 33539326, 2021). "Treatment of the TGF-β2-induced glaucoma model with Y27632 was shown to promote cytoskeleton reorganization and reduce the expression of both ECM and myocilin, indicating a potential interaction between the ROCK and TGF-β2 pathways." (PMID 32599818, 2020). "Given the Finnish enrichment of the known strong glaucoma risk allele, p.Gln368Ter, in MYOC (MAF in Finland = 0.3%, MAF in Non-Finnish European = 0.16%, reference sequence: NM_00026), we next asked whether carriers have risk reduced if they carry ANGPTL7 p.Arg220Cys." (PMID 32369491, 2020). "Collectively, these results suggest a molecular mechanism for the cross-talk between MYOC Y437H and TGF-β2 in the pathology of glaucoma." (PMID 32410836, 2020). "Other genes, including FOXC1, CYP1B1, LMX1B and MYOC were not expressed substantially in any neural retina cell classes, consistent with their proposed role predominantly in the anterior segment with mutations leading to high intraocular pressure, a major risk factor for glaucoma." (PMID 32555229, 2020). "Prior to undertaking experiments, cell types were validated by quantifying Myocilin (MYOC) mRNA/protein in control HTM-5 cells treated with Dexamethasone (DEX) and the expression levels of glaucoma-related genes in glaucomatous HTM-3 cells." (PMID 30931966, 2019).
glaucoma (continued). "Several mouse models over-expressing wt MYOC or MYOC mutant proteins have been established to study intraocular pressure (IOP) and glaucoma disease development." (PMID 30395621, 2018). "We also evaluated sequence variations in the myocilin (MYOC) gene, a gene that accounts for approximately 2–4% of glaucoma cases." (PMID 29064009, 2017). "The new connection to MYOC and exocytosis indicates FOXC1’s involvement in additional mechanisms related to glaucoma and further elucidates the mechanisms through which FOXC1 is involved in neurodevelopment and function." (PMID 28575017, 2017). "The gene has been mapped to the glaucoma locus, GLC1A where MYOC also resides and is known to be downregulated in cultured human TM cells." (PMID 28514956, 2017). "The new connection between MYOC and FOXC1 can improve our understanding of the role of FOXC1 in glaucoma pathogenesis." (PMID 28575017, 2017). "However, the lack of myocilin does not cause glaucoma, and in spite of considerable research efforts over the past 20 years, the normal functional role of wild type myocilin in the trabecular meshwork remains unclear." (PMID 26121352, 2015). "Thus the experimental observations are consistent with our proposed hypothesis that mutant CYP1B1, lacking the 17β estradiol metabolizing activity, can cause MYOC upregulation, which might have a potential implication in glaucoma pathogenesis." (PMID 23028769, 2012). "myocilin (MYOC), optineurin (OPTN), WDR36 and neurotrophin-4 (NTF4) in primary open angle glaucoma (POAG) and CYP1B1 and LTBP2 in congenital and developmental glaucomas." (PMID 21150032, 2011). "However, reduction or absence of the extracellular normal protein neither explains the apparently normal ocular phenotype in both hemizygous and homozygous MYOC-knockout mice, nor why mutations such as K423E, which causes glaucoma in heterozygotes, do not produce the disease in homozygotes." (PMID 19023451, 2008). "MYOC, OPTN, WDR36, and CYP1B1 have all been identified in a relatively small percentage of patients with various types of glaucoma, and it remains possible that these genes are abnormal with a small percentage of PEG patients." (PMID 18246027, 2008). ",18,34Myoc knockout mice or humans with homozygous deletions of MYOC do not exhibit glaucoma phenotypes, indicating that wild-type MYOC is not required for IOP regulation." (PMID 41210166, 2025). "Regarding genetic glaucoma models, we considered the main hallmarks and limitations of DBA/2J, glutamate/aspartate transporter/excitatory amino acid carrier 1, myocilin, connective tissue growth factor, optineurin, purinergic receptor 2Y, caveolin 1, and endothelin-1 mice." (PMID 41227293, 2025). "Given the variability of our results in MYOC gene expression upon treatment with EVs derived from imCSSCs, combined with the current lack of knowledge regarding its involvement in glaucoma pathogenesis, it is challenging to draw any definitive conclusions." (PMID 39847376, 2025). "This approach increases outflow facility in two mouse models of glaucoma (Tg-MYOCY437H myocilin model and the steroid-induced dexamethasone model), non-human primates (NHPs), and human donor eyes." (PMID 39423611, 2024). "The same applies to glaucoma, where complex Mendelian and non-Mendelian genetic mechanisms coexist, with multiple loci, such as MYOC, OPTN, and TBK1, each contributing to the variability and progression of glaucomatous neurodegeneration." (PMID 39766826, 2024). "Examples of these include genetic models of glaucoma (MyocY437H mice), OHT induced by transduction of the TM with glaucoma-related genes (e.g., MYOC, TGFβ2, GREM1, CTGF, DKK1, SFRP1, CD44, Cre and inducible transgene models, genome editing), as well as glucocorticoid-induced OHT models." (PMID 35129590, 2022). "Despite this, neither the normal functions of MYOC nor how MYOC mutations result in IOP elevation and subsequently glaucoma have been defined." (PMID 34834521, 2021).
glaucoma (continued). "Analysis of the combined RNA-Seq and ChIP-Seq data showed that the transcription of several of the differentially expressed genes with roles in TM, IOP, and glaucoma, were directly regulated by GLIS1 and included MYOC, LTBP2, CHI3L1, HMGA1, CYP1B1, and LOXL1-4." (PMID 34385434, 2021). "Standard PCR was performed to verify the size of all amplified products and amplification of ELAM-1, MGP and MYOC glaucoma-related genes was checked by sequentiation (data not shown)." (PMID 30931966, 2019). "Mutations in Myocilin (MYOC) have been observed more frequently than mutations in OPTN and WDR36, although most cases of glaucoma do not involve these genetic mutations." (PMID 30923720, 2019). "Western blots of ocular tissue lysates showed no detectable expression of the human mutant MYOC protein and this is the probable reason why these transgenics did not exhibit features of glaucoma." (PMID 30395621, 2018). "The UPR is known to be involved in myocilin-related glaucoma; our results suggest the UPR has a role in non-myocilin causes of HTG." (PMID 28264060, 2017). "COL1A1 analysis of the complete coding region by Sanger sequencing was then carried out in an independent cohort of 24 German patients diagnosed with congenital/early onset glaucoma that were found negative for mutations in CYP1B1 and MYOC genes." (PMID 27484908, 2016). "The three coding exons of MYOC were analyzed with PCR and sequencing in 207 index patients with various types of glaucoma and in 119 control individuals with no family history of ocular disorders." (PMID 23922489, 2013). "On the contrary, BAC mediated myocilin overexpression in mouse does not produce any glaucoma phenotype." (PMID 23028769, 2012). "While myocilin is a glaucoma gene, it is not always elevated at the protein level in TM tissues in open angle glaucoma." (PMID 22876128, 2012). "A novel heterozygous missense mutation c.1151 A>G in exon 3 of MYOC was found in all five patients diagnosed as POAG and four glaucoma suspects, but not in the rest of the family members and 102 normal controls." (PMID 22876119, 2012). "Myocilin (MYOC), a candidate gene for juvenile and adult onset forms of primary open angle glaucoma, may have been involved with CYP1B1 through a digenic mechanism in a glaucoma family of East Indian (Guyanese) origin." (PMID 21572728, 2011). "The mutant MYOC protein induces ER stress and the resultant UPR induces apoptosis in TM cells, which then leads to increased resistance to aqueous humor outflow, elevated IOP, and, ultimately, glaucoma." (PMID 20664690, 2010). "It was observed that, in culture media, very little to no mutant myocilin associated with the development of glaucoma was secreted out of the HTM cells, while WT and polymorphism variant myocilin were secreted normally." (PMID 20015381, 2009). "MYOCILIN (MYOC; OMIM 601652) was the first gene identified in glaucoma." (PMID 19023451, 2008). "Moreover, on the molecular level, LUT-EX@MN arrays reversed glaucoma-induced biochemical changes, such as the inflammatory markers; TNF-α, IL-8, and IL-1β, glaucoma-related biomarkers; MYOC, NRF2, and TIMP1 and the activity of glutathione peroxidase to levels comparable to healthy controls." (PMID 40643885, 2026). "Notably, human MYOC contains a peroxisome targeting signal absent in mouse Myoc, which is critical for mutant MYOC induced toxicity in TM cells; thus, the corresponding mouse Myoc did not develop the glaucoma phenotype." (PMID 38671671, 2024). "During a pilot study, the glycoprotein myocilin, which is a phenotypic marker of TMCs and is involved in the pathogenesis of glaucoma, was observed not to accumulate in whole-cell lysates of TMCs stimulated with dexa and epox, the most potent and selective proteasome inhibitor." (PMID 39337505, 2024). "However, other transgenic mouse lines expressing either mutant or wild-type myocilin did not develop glaucoma." (PMID 36077382, 2022).